SP1 (Sp1 transcription factor)
Diseases named in the same sentence as SP1 in open-access papers (continued):
Sharing a sentence is not in itself a finding about the gene and the disease.
glioma (continued). "Terameprocol is a global transcriptional inhibitor that induces cell cycle arrest by selectively inhibiting specific protein 1 (Sp1), and it has been studied in stages I and II of recurrent high-grade glioma." (PMID 36248799, 2022). "Under-expression of SP1 reduced the proliferation, migration, and invasiveness of U87 glioma cells in vitro as well as their tumorigenesis in vivo." (PMID 34445646, 2021). "Under-expression of SP1 in glioma cells also led to increased proliferation of CD8 (+) T cells and reduced the radio-resistance of U87 cells." (PMID 34445646, 2021). "In glioma, IL-6 promotes hypermethylation of the Sp1-binding site in the miR142-3p gene promoter, preventing binding of Sp1 and inhibiting miR-142-3p expression." (PMID 34168976, 2021). "miR‐5188, FOXO1, c‐JUN and SP1 expression were measured to illustrate their potential correlations in glioma and healthy brain tissues." (PMID 32902145, 2020). "miR‐5188 levels were negatively associated with FOXO1 mRNA levels (r = −0.3380, P = .0329), but positively correlated with c‐JUN mRNA levels (r = 0.2975, P = .0003) and SP1 mRNA levels (r = 0.2116, P = .0028) in the glioma specimens." (PMID 32902145, 2020). "Some literature has reported the expression of SP1 was dysregulated in various types of cancers including glioma." (PMID 32158359, 2020). "Through Kaplan–Meier survival analysis and Cox regression analysis, we proved that miR-4310, SP1, and PTEN can be used as risk factors for glioma prognosis." (PMID 33327965, 2020). "c‐JUN and SP1 mRNA levels were elevated in glioma in comparison with those in healthy brain tissues (P < .0001), whereas FOXO1 mRNA levels were down‐regulated in glioma (P = .0049)." (PMID 32902145, 2020). "In the current investigation, we identified the important role of miR‐5188 in glioma by examining miR‐5188 expression in glioma and non‐tumour brain specimens and the correlations between the expression of miR‐5188, SP1, c‐JUN and FOXO1." (PMID 32902145, 2020). "SP1 is a well‐known transcription factor and was shown to regulate non‐coding RNA expression to promote glioma progression." (PMID 32902145, 2020). "We found that the expression of CD147 induced by NE (10 μmol/L) was significantly reduced through Sp1 knockdown in two glioma." (PMID 33178600, 2020). "According to reports, SP1 plays an important role in the tumorigenesis, progression, and drug resistance of gliomas." (PMID 33327965, 2020). "Here, we confirmed CD147 as a direct target of Sp1 in glioma using bioinformatics binding site prediction, a dual luciferase reporting system and western blot analysis." (PMID 33178600, 2020). "For instance, Sp1 promoted progression of glioma, colon cancer and ovarian cancer and in these cases Sp1 all functions through elevating VEGFA." (PMID 33187481, 2020). "The results of this analysis show that the expression level of SP1 increases with the WHO grade of glioma." (PMID 33327965, 2020). "Among the members of the Sp family, both Sp1 and Sp4 were obviously increased in brain tumors, and Sp1 has been shown to promote glioma progression and drug resistance in numerous studies." (PMID 31717924, 2019). "The survival analysis based on the TCGA database demonstrated that the high level of SP1 indicated the poor prognosis of glioma patients." (PMID 30973678, 2019). "In summary, our study discovered the LINC00511 overexpression, inspired by the transcription factor SP1, in the glioma cells." (PMID 30973678, 2019). "The abundance of SP1 is verified to be increased in the glioma cells, and its overexpression is also correlated with the poor prognosis." (PMID 30973678, 2019). "Transcriptional factor specificity protein 1 (SP1) has been found to be up‐regulated in the glioma and participate the glioma genesis." (PMID 30973678, 2019).
glioma (continued). "Overall, our finding illuminates that LINC00511 is induced by SP1 and accelerates the glioma progression through targeting miR‐124‐3p/CCND2 axis, constructing the SP1/LINC00511/miR‐124‐3p/CCND2 axis." (PMID 30973678, 2019). "A recent study reported that miR-377 inhibited the proliferation and invasion of glioma cells though directly targetting SP1." (PMID 29654167, 2018). "In glioma, miR-377 suppresses the proliferation and invasion of tumor cells via targeted-regulation of SP1." (PMID 30305135, 2018). "Highly expressed miR-150-3p suppressed the growth of glioma cells partially via targetting the SP1-PTEN signaling pathway." (PMID 29654167, 2018). "Consistently, the expression level of SP1 in glioma cells including A172, U87-MG, SWO-38, U251, and SHG-44 was also notably increased in comparison with that of the normal cell NHA." (PMID 29654167, 2018). "Inverse correlation between the expression of miR-150-3p and SP1 was also observed in glioma tissues." (PMID 29654167, 2018). "Highly expressed miR-150-3p in glioma cells significantly decreased both the mRNA and protein levels of SP1." (PMID 29654167, 2018). "Both the mRNA and protein level of SP1 of glioma cells were increased with the reduction in miR-150-3p." (PMID 29654167, 2018). "Collectively, these results suggested that miR-150-3p suppressed the growth of glioma cells partially via regulating SP1 and possibly PTEN." (PMID 29654167, 2018). "The result showed that the expression of SP1 was significantly up-regulated in glioma tissues compared with that of the normal tissues." (PMID 29654167, 2018). "In particular, the increase of CYP17A1 was caused by Sp1-mediated DNA demethylation, whereby Sp1 competed with DNMT3a for binding to the CYP17A1 promoter in TMZ-resistant glioma cells." (PMID 28530704, 2017). "Our findings provide a novel understanding of the function of XIST/miR-29c/SP1/MGMT in the sensitivity of glioma to chemotherapy and the mechanism involved." (PMID 28831025, 2017). "In the present study, we found that CYP17A1 expression was significantly increased by Sp1 and correlated with poor prognosis in glioma patients." (PMID 28530704, 2017). "Our data suggest that XIST can amplify the chemoresistance of glioma cell lines to TMZ through directly targetting miR-29c via SP1 and MGMT." (PMID 28831025, 2017). "In human glioma cells, the Sp1 transcription factor acts as a positive regulator of GLUT3 expression." (PMID 29228563, 2017). "In human glioma, overexpression of Sp1 was demonstrated to increase the invasiveness of glioma cells via increased activity and expression of MMP-2, and was positively correlated with WHO grades of glioma." (PMID 27829234, 2016). "Our results indicated that miR-29c indirectly suppressed MGMT expression by targeting Sp1 in glioma cells." (PMID 27384876, 2016). "Guan and co-workers showed that Sp1 levels are high in glioma, and that Sp1 levels are correlated with tumor grade, and inversely correlated to patient survival." (PMID 26689994, 2016). "Using Spearman correlation analysis, we examined the association between endogenous miR-29c and Sp1, MGMT immunostaining intensity in human glioma tissues." (PMID 27384876, 2016). "Sp transcription factors Sp1, Sp3 and Sp4 are highly expressed in cancer cells/tumors and Sp1 is a negative prognostic factor for survival of gastric and pancreatic cancer and glioma patients." (PMID 26673922, 2015). "Hypoxia-mediated upregulation of Sp1 induces the expression of the metallopeptidase domain 17 (ADAM17) gene in the human glioma cell line U87, although the detailed mechanisms of this Sp1 induction are unclear." (PMID 26703734, 2015). "Validation of DDX3X-regulated genes found that DDX3X protein highly expresses in human glioma cells and correlates the protein level of SP1, and ESR1." (PMID 26184164, 2015). "Our findings first establish a role for the SNAI1/miR-128/SP1 axis in the regulation of glioma evolution." (PMID 24959930, 2014).
glioma (continued). "Immunohistochemistry and in situ hybridisation analysis of SNAI1, SP1 and miR-128 unraveled their expression levels and correlations in glioma samples." (PMID 24959930, 2014). "In our study, the mechanism of how the SNAI1/miR-128/SP1 axis facilitates glioma progression was investigated." (PMID 24959930, 2014). "Immunohistochemistry and in situ hybridisation staining were used for quantifying SNAI1, SP1 and miR-128 expression levels in human glioma samples." (PMID 24959930, 2014). "The downregulation of Sp1 by Sp1 ribozyme correlated with increased apoptosis, and the silencing of Sp1 by siRNA suppressed invasion in human glioma cells." (PMID 23403540, 2013). "We recently reported that PLD enhances expression of the MMP-2 gene by increasing the DNA binding activity of NFκB and Sp1, and then promotes glioma cell invasion." (PMID 20711340, 2010). "In this study, we investigated if Sp1 protein plays a role in ADAM17 transcription, and if Sp1 regulates hypoxic-induced ADAM17 expression in U87 human glioma cells." (PMID 19772640, 2009). "The normal brain-derived and glioma cells were found to contain SP1 when studied by radioimmunoassay and by the triple-bridge immunoperoxidase technique." (PMID 7018548, 1981). "A specific example is XIST-mediated sequestration of miR-29c in glioma, leading to increased expression of oncogenic targets such as transcription factor specificity protein 1 (SP1) and O6-methylguanine-DNA methytransferase (MGMT) and promoting tumor progression and chemoresistance." (PMID 41601966, 2026). "SP1 regulates the expression of genes involved in cell division, proliferation, apoptosis, and angiogenesis and it has been reported to be overexpressed in certain cancers, including glioma." (PMID 39915450, 2025). "Indeed, it has been shown that miR-150-3p is downregulated in glioma tissues and cell lines, and its overexpression inhibits glioma cell growth by targeting the transcription factor specificity protein 1 (SP1)." (PMID 39915450, 2025). "It was striking that SP1 is a significant marker of gliomas in the brain." (PMID 41279024, 2025). "HDAC1/2/6/Sp1 activation is bound up with poor prognosis in suffers with glioma." (PMID 39068393, 2024). "SP1 transcriptionally activated NLRP6 to induce radioresistance in glioma cells." (PMID 38589918, 2024). "Moreover, knockdown of SP1 strongly reduces MGMT protein expression, further suggesting SP1’s role as a main regulating factor for MGMT expression in glioma cells." (PMID 38521933, 2024). "Additionally, SP1 can induce LINC01614 expression to enhance the malignant development of gliomas via the miR-383/ADAM12 pathway." (PMID 39596660, 2024). "Our results supported that Sp1-dependent Gαi2 transcription was increased in glioma tissues and cells, which might be one primary mechanism of Gαi2 upregulation in glioma." (PMID 36778118, 2023). "In addition, immunohistochemical (IHC) staining and Western blot analyses of clinical glioma tissue samples revealed a strong positive correlation between SP1 and TRIM56 expression." (PMID 36870986, 2023). "The miR-21/SP1/DNMT1 positive feedback loop in MSCs triggered by glioma exosomal CD44 could increase MSC exosomal miR-21 to a dozen times that in glioma exosomes, amplifying glioma exosomal immunosuppressive signaling." (PMID 37481646, 2023). "The findings indicate that Sp1 could potentially serve as a molecular indicator for the antineoplastic properties of oHSV-1 in managing glioma." (PMID 37880659, 2023). "Sp1 mRNA and protein expression was robustly decreased in shSp1 and koSp1 P1 glioma cells." (PMID 36778118, 2023). "Sp1 protein levels were remarkably upregulated in oeSp1 P1 glioma cells." (PMID 36778118, 2023). "Therefore, the increase of Sp1-dependent transcription should be one key mechanism of Gαi2 overexpression in human glioma." (PMID 36778118, 2023). "In glioma cells Gαi2 expression was downregulated after Sp1 silencing, KO or inhibition." (PMID 36778118, 2023).
glioma (continued). "Besides, Sp1 is over-expressed in brain glioma cancer and can facilitate proliferation and invasion of glioma cells." (PMID 35778451, 2022). "Moreover, we demonstrated Sp1 interact with the TIMP1 promoter to upregulate its expression in glioma cells." (PMID 35778451, 2022). "Furthermore, miR-375 and miR-130a-3p have been reported to target Sp1 in glioma to suppress tumor progression and temozolomide (TMZ) resistance." (PMID 33472586, 2021). "Furthermore, enhanced SP1 mRNA level tended to result in a poor clinical outcome of liver hepatocellular carcinoma and brain lower grade glioma, suggesting its vital role in tumorigenesis." (PMID 34257529, 2021). "Collectively, we considered that SP1 was responsible for the upregulation of LBX2-AS1 in glioma." (PMID 34729101, 2021). "A consecutive miR‐5188 knockdown could overcome the stimulatory effects of SP1 overexpression in glioma cells, as measured using MTT and Edu assays." (PMID 32902145, 2020). "Importantly, we revealed that the SP1/miR-4310/PTEN axis activates the PI3K/AKT signaling pathway to promote glioma progression." (PMID 33327965, 2020). "Our investigation demonstrates that miR‐5188 could function as a tumour promoter by directly targeting FOXO1 and participating in SP1‐mediated promotion of cell growth and tumorigenesis in glioma." (PMID 32902145, 2020). "Furthermore, we also found that levels of c‐JUN were decreased after SP1 knockdown through Western blotting in glioma cells, suggesting the regulation of SP1 on PI3K/AKT‐c‐JUN pathway." (PMID 32902145, 2020). "Moreover, we demonstrated that miR-128-3p targeted SP1, corroborating previous findings that miR-128 plays an essential role in glioma progression via SP1 suppression." (PMID 33424542, 2020). "Together, these results suggest that miR-181b could inhibit glioma growth via targeting SP1 in vivo." (PMID 32158359, 2020). "Finally, we analyzed 86 paraffin-embedded glioma tissue samples and found a positive correlation between miR-4310 and SP1." (PMID 33327965, 2020). "Here, we showed that SP1 enhanced miR‐5188 expression to promote glioma cell growth and metastasis." (PMID 32902145, 2020). "SP1 mRNA tested by the PCR revealed its up‐regulation in the glioma cells (U87, U251)." (PMID 30973678, 2019). "Therefore, data confirm that the transcription factor SP1 accelerates the transcription of LINC00511 in glioma cells." (PMID 30973678, 2019). "Furthermore, the correlation between the expression of SP1 and miR-150-3p in glioma tissues was also analyzed." (PMID 29654167, 2018). "Combined with our results, SP1 was a promising target of different miRNAs in glioma that might function together to inhibit the carcinogenesis of glioma." (PMID 29654167, 2018). "As reported, aberrant over-expression of Sp1 in human glioma promoted MMP2-mediated cell invasion." (PMID 29262634, 2017). "Because the Sp1 transcription factor is a positive regulator of GLUT3 expression in human glioma cells, at first, we tested its mRNA expression and could not detect any changes when treating with riluzole (data not shown)." (PMID 29228563, 2017). "Interestingly, CYP17A1 knockdown abolished Sp1-enhanced invasiveness, thus further suggesting that Sp1-mediated CYP17A1 expression is required for glioma malignancy." (PMID 28530704, 2017). "Our study provides the first evidence that starvation caused by radiation might play a significant role in enhancing the ability of the glioma cell line U251 to metastasize via regulation of the transcription factor SP1." (PMID 27058528, 2016). "We show that the SP1 expression increasing the response to TMZ in glioma cell lines." (PMID 27384876, 2016). "SP1 was selected for further analysis as there have been many studies on its role in cell cycle, tumor formation, growth and migration, but with very few reports in the context of gliomas." (PMID 24959930, 2014).
glioma (continued). "We propose that the SNAI1/miR-128/SP1 axis, which plays a vital role in glioma progression, may come to be a clinically relevant therapeutic target." (PMID 24959930, 2014). "Importantly, Gαi2 mRNA/protein levels were reduced in Sp1-depleted P1 glioma cells." (PMID 36778118, 2023). "Therefore, Sp1 and Gαi2 promoter binding increasing could be an important mechanism of Gαi2 upregulation in human glioma tissues and cells." (PMID 36778118, 2023). "We first tested whether Sp1 was important for Gαi2 expression in glioma cells." (PMID 36778118, 2023). "Moreover, circSCAF11 positively mediated sp1 expression via interacting with miR-421 in glioma." (PMID 34499009, 2021). "Besides, Western blotting revealed that miR‐5188 inhibition led to reduced protein levels of P‐PI3K, P‐AKT, CCND1, CDK4 and c‐JUN, but increased protein levels of FOXO1 in glioma cells with SP1 overexpression, suggesting that miR‐5188 was enhanced by SP1 through the PI3K/AKT pathway." (PMID 32902145, 2020). "Due to the multiple targets of miRNAs, in addition to SP1, searching for other downstream targets of miR-150-3p and related pathways that might partially mediate the role of miR-150-3p in glioma cells is also an interesting topic to provide novel insights into the function of miR-150-3p in glioma." (PMID 29654167, 2018). "Additionally, ZFAS1 could exhibit a tumor oncogenic role by regulating EMT and Notch signaling pathway in glioma and it facilitated ovarian cancer cell malignancy by participating in miR-150-5p/Sp1 axis." (PMID 28977885, 2017). "The recent report indicated that SP1 transcriptionally activates NLRP6 inflammasome to trigger immune evasion and radioresistance in glioma cells." (PMID 38166970, 2024). "Its predicted target genes include four hub genes, CCND1, SP1, CDK6 and CDK4, which are directly or indirectly involved in glioma development." (PMID 39348350, 2024). "In glioma, the upregulation of LINC01614 by SP1 promoted cancer progression by regulating the miR-383/ADAM12 axis." (PMID 38655053, 2024). "Further study showed that the miR-21/SP1/DNMT1 positive feedback loop in MSCs triggered by glioma exosomal CD44 upregulated MSC exosomal miR-21 expression, amplifying the glioma exosomal immunosuppressive signal." (PMID 37481646, 2023). "In research, it was found that the epidermal growth factor receptor activation in the glioma is induced by COX-2 (cyclooxygenase 2-self-dependent prognostic factor in glioma) expression, through P38 mitogen activation of SP1/SP3." (PMID 37298889, 2023). "In contrast, E3 ligase TRIM56 is transcriptionally upregulated by SP1 and impacts IQGAP1-CDC42 signaling to facilitate glioma migration and invasion." (PMID 37723588, 2023). "In gliomas, hypomethylation of the promoter region of SNHG12 was correlated with the transcription factor SP1, leading to its up-regulation in temozolomide-resistant cell lines." (PMID 35406435, 2022). "miR-128 plays a negative regulatory role in the SNAI1/miR-128/SP1 axis, counteracting this role of SNAI1 in promoting glioma progression and inhibiting glioma aggressiveness." (PMID 36479040, 2022). "Hypoxia-induced SP1 expression led to increased activation of disintegrin and metalloproteinase-17 (ADAM17) promoter, enhancing glioma’s invasiveness under hypoxic conditions." (PMID 36077352, 2022). "Another study reported that, through the regulation of ADAM12, SP1-mediated upregulation of lncRNA LINC01614 functions as a ceRNA for miR-383, thereby facilitating glioma progression." (PMID 33889541, 2021). "Mechanistic experiments further indicated that circSCAF11 accelerated glioma tumorigenesis through the miR-421/SP1/VEGFA axis, providing a potential target for circRNAs and glioma treatment." (PMID 33407501, 2021). "The DNA repair proteins MGMT and SP1 play important roles in TMZ resistance and are upregulated in TMZ-resistant glioma cell lines." (PMID 34316694, 2021).